CCL26 (C-C motif chemokine ligand 26)
Description:
Chemoattractant for eosinophils and basophils. Acts as a ligand for C-C chemokine receptor CCR3 which triggers Ca(2+) mobilization in eosinophils. Also acts as a ligand for CX3C chemokine receptor CX3CR1, inducing cell chemotaxis.
Synonyms: TSC-1; SCYA26; MIP-4alpha; eotaxin-3; IMAC; MIP-4a
Tractability: Antibody: UniProt places it where antibodies can reach, with high confidence; UniProt predicts a signal peptide or a membrane-spanning region; its Gene Ontology location is reachable by antibodies, with medium confidence.
Gene: Protein-coding gene on chromosome 7 (75,769,533 to 75,789,896, reverse strand). Ensembl gene ENSG00000006606.
Subcellular location: Secreted
Gene Ontology:
Molecular function: CCR3 chemokine receptor binding; chemokine activity; CX3C chemokine receptor binding; protein binding; receptor ligand activity; CCR chemokine receptor binding
Biological process: cell chemotaxis; chemokine-mediated signaling pathway; monocyte chemotaxis; positive regulation of actin filament polymerization; positive regulation of cell migration; positive regulation of chemotaxis; positive regulation of endothelial cell proliferation; T cell chemotaxis; antimicrobial humoral immune response mediated by antimicrobial peptide; cell-cell signaling; chemotaxis; eosinophil chemotaxis; inflammatory response; signal transduction; immune response
Cellular component: extracellular region
Genetic constraint (gnomAD): Loss-of-function variants: 6 observed, 5.96 expected, observed/expected ratio (o/e) 1.01, 90% interval 0.54 to 1.78. That is too few expected variants to judge how well the gene tolerates losing a copy. Missense variants: 65 observed, 67.26 expected, observed/expected ratio (o/e) 0.97, 90% interval 0.79 to 1.19. Synonymous variants: 22 observed, 26.81 expected, observed/expected ratio (o/e) 0.82, 90% interval 0.58 to 1.17.
Homologues: Orthologues: chimpanzee CCL26 (97% identical), macaque CCL26 (85% identical), pig CCL26 (65% identical), dog CCL26 (60% identical), rat Ccl24 (49% identical), zebrafish ccl35.1 (31% identical), zebrafish ccl35.2 (31% identical). Paralogues in human: CCL13 (37% identical), CCL14 (36% identical), CCL18 (36% identical), CCL21 (36% identical), CCL3L3 (36% identical), CCL4 (36% identical), CCL5 (36% identical), CCL3 (35% identical), CCL7 (35% identical), CCL11 (34% identical), CCL24 (34% identical), CCL8 (34% identical), and 14 more.
Diseases named in the same sentence as CCL26 in open-access papers:
CCL26 is named in the same sentence as 108 diseases in open-access papers, as found by Europe PMC text mining. Sharing a sentence is not in itself a finding about the gene and the disease. The quoted sentences say what the papers report.
asthma (46 papers, 2012 to 2025). "CCL26/eotaxin-3 has been associated with more severe asthma and has been shown to induce a stronger eosinophil migratory response." (PMID 41013452, 2025). "Our results indicate that the overexpression of CCL26 as well as CST1 causes a downregulation of several antiviral response genes which has previously been seen in patients with asthma and allergy." (PMID 38270326, 2024). "Asthma’s hallmark, lung eosinophilia, is induced by eotaxins-3 (CCL26), a crucial chemokine in the pathophysiology of asthma." (PMID 39125822, 2024). "Although the findings are from nasal epithelium, they are in line with our hypothesis that the overexpression of CCL26 causes a more severe asthma phenotype, based on previous findings in nasal epithelium." (PMID 38270326, 2024). "In line with this function, CCL26 has been linked to asthma in several previous studies." (PMID 38270326, 2024). "Furthermore, CCL26 has also been described as produced by human bronchial epithelial cells and keratinocytes and its imbalanced secretion, probably due to an overexpression of type-2 cytokines, was implicated in atopic dermatitis and asthma." (PMID 35799778, 2022). "The link between CCL26 and asthma has been established in several studies, highlighting its role in disease development." (PMID 40370530, 2025). "Our findings align with these observations and identify inhibition of CCL26 release from the lung epithelium as one potential mechanism of action behind the therapeutic efficacy of IL-4Rα biologics in asthma." (PMID 40370530, 2025). "CCL26 plays a significant role in asthma by attracting CCR3-expressing cells including eosinophils, basophils, and T2 lymphocytes." (PMID 40370530, 2025). "Our results highlight the role of CST1 and CCL26 in asthma development due to their role in inflammation." (PMID 38270326, 2024). "Increased expression of CST1 and CCL26 has been previously shown in nasal epithelium of children with asthma and allergy, however, the functional mechanism of how it contributes to asthma development is so far not well understood." (PMID 38270326, 2024). "Elevated levels of CCL26, both in CSF and blood serum, have been observed in numerous diseases, including Alzheimer’s disease, asthma, rheumatoid arthritis, cancer, and experimental autoimmune encephalomyelitis." (PMID 37893015, 2023). "IL‐4, IL‐5 and CCL26 were significantly higher in T2‐high‐FNS compared with both T2‐low asthma and healthy controls." (PMID 35579040, 2022). "Genes upregulated by T2 cytokines and that have been associated with T2 asthma included the eosinophil chemoattractant CCL26 and POSTN (periostin) which is implicated in extracellular matrix remodeling, both biological processes associated with asthma." (PMID 32560723, 2020). "CCL26 is the most potent eosinophil attracting factor and its increased level in the serum is correlated with the severity of asthma." (PMID 27010397, 2016). "It is well known that eosinophils that respond to a variety of CC chemokines, such as CCL11 (eotaxin), CCL24 (eotaxin-2) and CCL26 (eotaxin-3), are proinflammatory granulocytes with significant roles in several inflammatory diseases, including asthma." (PMID 27304950, 2016). "The ability of siRNA treatment to attenuate IL-13-induced CCL26 in primary NEC's from asthma patients further supports the therapeutic potential of this approach." (PMID 23402658, 2013). "IL-4Rα mAb treatment effectively inhibited CCL26 production in BECs from asthma patients." (PMID 40370530, 2025). "Notably, the increase in CCL26 protein levels was significantly higher in BECs from asthma donors compared with healthy donors." (PMID 40370530, 2025). "Therefore, the aim was to investigate the functional mechanisms of CST1 and CCL26 in an alveolar basal epithelial cell line to understand their function in asthma pathogenesis better." (PMID 38270326, 2024).
asthma (continued). "Additionally, we examined the levels of inflammatory cytokines in sputum and found that IL‐5, IL‐6, IL‐8, TNF‐α, IFN‐γ, CCL17, CCL22, CXCL10, CCL4, CCL2, IL‐4, IL‐13, and CCL26 were significantly lower in stable asthma than in acute asthma." (PMID 39508721, 2024). "Obtaining more knowledge about the mechanistic insights of those genes, it might be possible to identify whether CST1 and CCL26 can be potential drug targets for asthma treatment." (PMID 38270326, 2024). "Even though several studies showed an association between increased levels of CST1 and CCL26 and the development of asthma, it was to our knowledge so far not possible to understand the contribution of CST1 and CCL26 in the disease development." (PMID 38270326, 2024). "Increased serum levels of the chemokine CCL26/eotaxin-3 could differentiate moderate-to-severe asthma from healthy controls, and recent findings point out the ability of CCL17/TARC to predict type-2 eosinophilic asthma." (PMID 36835081, 2023). "Furthermore, local expression of the chemokines CCL-11 (eotaxin-1) and CCL-26 (eotaxin-3) is increased in asthma and allergic rhinitis." (PMID 36679633, 2023). "Notably, AEC and NEC-derived correlated gene signatures including CCL26, CLCA1 and POSTN were involved in IL-13 signaling, where IL-13 signaling of the airway epithelium is associated pathophysiology of asthma and airway inflammation." (PMID 37438356, 2023). "Interestingly, previous studies with peripheral blood mononuclear cells also suggested CCL26 as a potential IL-13-related biomarker in the context of asthma and our findings, in unmanipulated donor nasal epithelial cells, support this." (PMID 23402658, 2013). "We included CCL26 (eotaxin-3) and CHI3L1 (chitinase-3-like-1) expression in this panel, as in addition to their involvement in asthma pathogenesis, their expression is also linked to epithelial differentiation, with both being members of gene families identified as potential asthma biomarkers." (PMID 23402658, 2013). "In spite of similar tissue cellular inflammation, sputum IL‐4, IL‐5 and CCL26 were increased in T2‐high versus T2‐low asthma, and several further T2‐associated cytokines, PGD2 and LTE4, were increased in T2‐high and T2‐intermediate asthma compared with healthy controls." (PMID 35579040, 2022). "By reducing and normalizing key inflammatory mediators such as CCL26 and TSLP, while preserving essential antiviral defense mechanisms, IL-4Rα blockade offers a balanced approach to managing asthma symptoms and preventing exacerbations." (PMID 40370530, 2025). "Therefore, CST1 and CCL26 might be considered as potential drug targets for asthma treatment." (PMID 38270326, 2024). "IL‐5, CCL17, CCL26 and TSLP concentrations were elevated significantly in asthma overall compared with health." (PMID 35579040, 2022). "Many other pathways were also identified that are regulated by IL-13 and relevant to asthma pathogenesis (e.g. CCL17, CCL26, CTGF, FCER1A, KITLG, MUC2, NOS2, TLR3)." (PMID 29367592, 2018). "In this study, ITLN-1 mRNA significantly correlated with FeNO and serum IgE, as well as iNOS, CCL26, periostin and DPP4 mRNA in SN-Asthma, as these genes are known to be induced in BECs stimulated with IL-13." (PMID 28775743, 2017). "In the SN-Asthma group, ITLN-1 mRNA correlated with FeNO, IgE, iNOS, CCL26, periostin and DPP4 mRNA, all Type-2 related parameters." (PMID 28775743, 2017). "The sputum inflammatory mediator profiles were distinct with increased TH2 (IL-5, IL-13, and CCL26) and TH1 mediators (CXCL10 and 11) in severe asthma compared with COPD and increased IL-6, CCL2, CCL3, and CCL4 in COPD compared with severe asthma." (PMID 25129678, 2015). "Moreover, miR-221 was described to correlate with airway eosinophilia in asthma and further increased CCL-24, CCL-26, and POSTN in asthmatic airways." (PMID 36172292, 2022).
asthma (continued). "We examined serum chemokine (CCL4, CCL11, CCL26, and CCL17) and total IgE serum levels, fractionated exhaled nitrogen oxide (FENO), and CCL4 expression in nasal polyps in patients with severe ECRS and asthma." (PMID 35892679, 2022). "In asthma (particularly T2-high severe asthma), eosinophils are actively recruited to airway tissues in response to chemokines upregulated by IL-4 and IL-13 such as eotaxin-1 (CCL11), eotaxin-2 (CCL24), and eotaxin-3 (CCL26), which binds to CCR3 receptors on eosinophils." (PMID 40004192, 2025). "Also, several inflammatory mediators, of potential relevance to asthma, such as SOCS1, IL1B, IL13RA1 and CCL26 could be potentially affected, directly or indirectly by one or more microRNAs of this list." (PMID 25360780, 2014). "Notably, si372 treatment also attenuated the ability of IL-13 to up-regulate CCL26 mRNA expression in primary NEC cultures, again irrespective of donor asthma status." (PMID 23402658, 2013).
eosinophilic esophagitis (23 papers, 2012 to 2025). Eosinophilic esophagitis (EoE) is a chronic, allergic disease of the esophagus characterized clinically by symptoms of esophageal dysfunction (including vomiting, dysphagia, feeding disorders, food impaction and abdominal pain) which persist after treatment with proton pump inhibitors (PPIs). "Significantly elevated gene levels of CCL26 are found in eosinophilia-associated diseases, such as eosinophilic esophagitis and eosinophilic gastritis, where transepithelial migration of eosinophils is one of the key steps for pathogenesis." (PMID 35742962, 2022). "In addition, STAT-6 regulates CCL26 expression in esophageal cells and it has been strongly associated with inflammation in esophageal biopsies from patients with eosinophilic esophagitis." (PMID 35799778, 2022). "Nonetheless, when eosinophils are accumulated in the esophagus, they can cause eosinophilic esophagitis, where eosinophils are recruited in response to IL-13, CCL26/eotaxin-3, and TGF-β, causing inflammation." (PMID 34209213, 2021). "It has been shown that CCL26 is the most overexpressed in patients with eosinophilic esophagitis (EE), a disease characterized by the accumulation of eosinophils in the esophagus and that CCL26 has a crucial role in eosinophil recruitment in EE." (PMID 23991422, 2013). "Notably, CCL26 was the most highly induced gene in patients suffering from eosinophilic esophagitis, a chronic allergic inflammation of the esophageal mucosa, compared with its expression level in healthy individuals." (PMID 34732256, 2021). "CCL26 is responsible for recruitment of eosinophils to the mucosa, and is strongly upregulated in the chronic inflammatory condition, eosinophilic esophagitis and therefore, its abundance in circulation in the EAC setting could also reflect advantageous mucosal inflammation." (PMID 33202734, 2020).
COVID-19 (15 papers, 2021 to 2025). A disease caused by infection with severe acute respiratory syndrome coronavirus 2. "Six proteins showed sex differences in levels over time, of which 3 were also associated with severe COVID-19: CCL26, IL1RL2, and IL3RA, providing insights to better understand the marked differences in outcomes by sex." (PMID 36171541, 2022). "Previously, CCL26 was found to be upregulated in patients with COVID-19 vs. HCs in plasma and correlates with disease severity." (PMID 37047248, 2023). "Levels of CCL26 (also known as eotaxin-3) were increased in COVID-19 patients and correlated with disease severity." (PMID 33232303, 2021). "Further CCL26 (also known as eotaxin-3) is known to induce eosinophils tissue infiltration, which could influence COVID-19 outcomes." (PMID 36171541, 2022). "None of the other measured mediators related to eosinophils and the T2 response (CCL26, IL-3, IL-4, IL-5, CD44, TSLP, or GM-CSF) displayed any significant differences between the different timepoints and between COVID-19 versus controls." (PMID 40710346, 2025). "Several proteins related to innate immune cell activation are upregulated in patients with COVID-19, such as FOLR2, anti-inflammatory macrophage markers, and CCL26." (PMID 37047248, 2023). "The findings showed that compared to healthy controls, patients with COVID-19 had significantly higher levels of interleukins 1α, 2, 6, 7, 8, 10 and 15, CRP, SAA, ICAM-1, VCAM-1, CXCL10, CCL3, CCL26, IFN-γ, TNF-α, bFGF, PlGF, and Flt-1." (PMID 35958594, 2022). "Levels of IL-6, IL-10, IL-15, IFN-γ, TNF-α, CCL2, CCL3, CCL4, CCL26, CXCL9 and CXCL10 were significantly elevated both in COVID-19 critical clinical condition and in MAS patients as compared to healthy controls." (PMID 34226537, 2021). "However, our observations on TLR5, CXCL17, CCL26, IL1RL2, and IL3RA provide clear proteins to explore to explain sex differences in COVID-19 outcomes." (PMID 36171541, 2022). "However, the robust study design and statistical analysis as well as the consistencies with previous studies, such as the upregulation in patients with COVID-19 of ACE2, FGF21, CCL26 and VWF among others, suggest the potential validation of these novel findings." (PMID 37047248, 2023). "Compared to the healthy controls, patients with COVID-19 had significantly higher circulating concentrations of 19 inflammatory mediators, namely interleukins 1α, 2, 6, 7, 8, 10 and 15, CRP, SAA, ICAM-1, VCAM-1, CXCL10, CCL3, CCL26, IFN-γ, TNF-α, bFGF, PlGF and Flt-1 (P < 0.05)." (PMID 35958594, 2022).
nasal polyps (14 papers, 2016 to 2025). "Notably, mRNA expression of CCL4, but not other well-known eosinophil-associated chemokines, such as CCL5, CCL11, and CCL26, was significantly higher in nasal polyps of patients with ECRS than in uncinate tissues of the same patients." (PMID 36555793, 2022). "Serum CCL26/Eotaxin-3 levels was positively correlated with the number of reactions to NSAIDs (r=0.33, p=0.03) and negatively with the age of diagnosis of nasal polyps (r=-0.38, p=0.03)." (PMID 41573581, 2025). "The increased expression of 15LO1 was observed in the epithelial cells of nasal polyps; 15LO1 also correlates with CCL26 expression and colocalizes with CCL26 in basal cells." (PMID 37762530, 2023). "Levels of IL-4, IL-5, IL-13, and ECP and the eotaxins CCL11, CCL24, and CCL26 were elevated in the nasal polyps of patients with eCRSwNP or noeCRSwNP." (PMID 35747690, 2022). "Recently, CCL4, CCL5, CCL11, and CCL26 expressions were found to be higher in nasal polyps than in uncinate process tissue in the same patients with ECRS." (PMID 36555793, 2022). "The expression of CCL4 and other eosinophilic chemoattractants (CCL5, CCL11, and CCL26) was reported to be increased in nasal polyps compared with that in uncinate process tissues of the same patients with ECRS." (PMID 36555793, 2022). "The eosinophilic chemo-attractants CCL4, CCL5, CCL11, and CCL26 were increased in nasal polyps compared with uncinate process tissues." (PMID 32085629, 2020). "Chemokines secreted by epithelial cells include eotaxin-1 (CCL11), eotaxin-2 (CCL24) and eotaxin-3 (CCL26) which have been demonstrated in increased numbers in nasal polyps as compared to healthy controls." (PMID 29376948, 2016). "This suggested that CCL26 might promote the development of nasal polyps and played a more significant role in eCRSwNP." (PMID 38280891, 2024). "Notably, CCL4 expression, but not CCL5, CCL11, or CCL26, was found to be significantly increased in nasal polyps from patients with ECRS associated with eosinophil infiltration as well as in BEAS-2B cells co-incubated with eosinophils." (PMID 36555793, 2022). "In nasal polyps, immunoreactivity of the chemokine ligand (CCL) eotaxin subfamily comprising eotaxin-1 (CCL11), eotaxin-2 (CCL24), and eotaxin-3 (CCL26) was noted." (PMID 30778348, 2019). "The results have revealed the key cell subsets that may be involved in forming nasal polyps and nasal mucosa inflammation and identified WFDC2 and CCL26 as the key genes involved in developing CRSwNP." (PMID 38280891, 2024).